SP1 (Sp1 transcription factor)
Diseases named in the same sentence as SP1 in open-access papers (continued):
Sharing a sentence is not in itself a finding about the gene and the disease.
ovarian tumor (2 papers, 2015 to 2023). "SP1 up regulated the SNHG7 that interacted with EZH2 to inhibit KLF2 expression in ovarian tumor cells." (PMID 37807067, 2023). "KLF2 recruited the SP1/CPBP to down regulate the WEE1 that sensitized ovarian tumor cells toward the DNA damage mediated apoptosis." (PMID 37807067, 2023). "Similar to the parental MTA, DIG-MSK potently inhibited Sp1-mediated transcription in these ovarian tumor cells, and, given that the Sp1 gene is autoregulated in a positive feedback, DIG-MSK was also a potent inhibitor of endogenous Sp1 expression." (PMID 26536461, 2015).
papillary thyroid cancer (2 papers, 2021 to 2025). "SP1 specifically binds to the promoter region of linc00313, plays a role in promoting transcription, and enhances the proliferation, migration, and invasion ability of papillary thyroid cancer cells." (PMID 33542193, 2021).
pituitary tumor (2 papers, 2020 to 2025). A benign or malignant neoplasm affecting the pituitary gland. "It was reported that HIF1A can suppress the transcription of PKA regulatory subunit 2B (PRKAR2B) by sequestering SP1 from the PRKAR2B promoter in human growth hormone–secreting pituitary tumors." (PMID 40493409, 2025). "However, HIF-1α co-immunoprecipitated with Sp1 in hypoxic GH3 cells confirming their physical interaction in pituitary tumor cells." (PMID 32111982, 2020).
pulmonary TB (2 papers, 2020 to 2022). "In active pulmonary TB patients with high bacterial burden, miR-23a-3p expression was decreased, affecting the balance between TLR4 and IL10 immunologic responses by down-regulating SP1/IRF1 expression and further influencing TLR4/IL10 expression ratio." (PMID 33202583, 2020).
rectal adenocarcinoma (2 papers, 2022). "In addition, Sp1 expression was positively associated with DDX39B in colon and rectal adenocarcinoma patients from the TCGA database." (PMID 35973989, 2022). "We also found a positive correlation between Sp1 and DDX39B in colon and rectal adenocarcinoma patients from the TCGA database." (PMID 35973989, 2022). "Heterozygous amplifications of ETS2 and CDK6 in TGCT; CDK6 in GBM; E2F1 and ID1 in rectum adenocarcinoma (READ); and SP1, CDK4, and MDM2 in ACC were all greater than 70%." (PMID 35911954, 2022).
rectal cancer (2 papers, 2016 to 2025). A primary or metastatic malignant neoplasm that affects the rectum. "Studies in rectal cancer have shown that Specificity Protein 1(Sp1) is involved in the upregulation of TRF2 expression, suggesting that SP1 may contribute to the stable replication of cancer cells through this mechanism, thereby potentially facilitating cancer progression." (PMID 39871386, 2025).
salivary gland cancer (2 papers, 2002 to 2009). A primary or metastatic malignant neoplasm that affects the major or minor salivary glands. "We have previously demonstrated that vesnarinone directly activates p21waf1 gene promoter via Sp1 sites in a human salivary gland cancer cell line." (PMID 19671192, 2009).
seminoma (2 papers, 2023 to 2025). A radiosensitive malignant germ cell tumor found in the testis (especially undescended), and extragonadal sites (anterior mediastinum and pineal gland). "However, within our pre-diagnostic data, we did not see MYC or SP1 as eigengenes in any of the seminoma or non-seminoma modules." (PMID 39809819, 2025). "In particular, the transcription factor-target gene pairs, MYC and SP1, were found to be common eigengenes in both seminoma and non-seminoma, as well as the miRNA miR-182-5p32." (PMID 39809819, 2025).
squamous cervical cancer (2 papers, 2015 to 2020). "Similar to our results, miR-375 is reduced in squamous cervical cancer and the up-regulation of miR-375 inhibits cell migration and invasion through suppressing transcription factor SP1." (PMID 31927536, 2020).
tuberculosis (2 papers, 2021 to 2024). A chronic, recurrent infection caused by the bacterium Mycobacterium tuberculosis. "Moreover, miR-23a-3p was shown to inhibit monocyte function and phagocytosis by targeting IRF1/SP1 followed by the TLR4/TNF-α/TGF-β1/IL-10 signaling pathway in patients with active tuberculosis." (PMID 34608568, 2021).
Wilms tumor (2 papers, 2015 to 2020). An embryonal neoplasm characterized by the presence of epithelial, mesenchymal, and blastema components. "The IGF-IR gene promoter also includes cis-elements for members of the early growth response family of zinc-finger proteins including the WT1 Wilms’ tumor suppressor, which, in contrast with Sp1, downregulates the expression of IGF-IR." (PMID 25884514, 2015). "By analyzing nucleotide sequences (see Chapter 2.2), we discovered in the −90/−52 region of most 7SL RNA and 4.5SH RNA genes sites corresponding to the GC-box consensus (GGGCGG or CCGCCC), which can potentially bind pol II transcription factors, such as Sp1, Krox/Egr, Wilms’ tumor, MIG1, and CREA." (PMID 32466110, 2020).
abscesses (1 paper, 2009). "Whole ZPS-positive commensal bacteria or their ZPS, such as Sp1, induce intraperitoneal abscesses when applied intraperitoneally with sterile cecal content (SCC) adjuvant." (PMID 19779562, 2009). "To study CD8+ T cell immunity to ZPS, we first employed a well characterized experimental model of CD4+ T cell-dependent immune response, which is the mouse model of Sp1-mediated abscess formation." (PMID 19779562, 2009). "Immunohistochemical analysis of Sp1-mediated intraperitoneal abscesses shows that CD8+ T cells participate in the formation of the organized wall of abscesses." (PMID 19779562, 2009). "In contrast, challenging C57BL/6 WT mice with intraperitoneal Sp1 plus adjuvant results in the formation of sterile abscesses six days later." (PMID 19779562, 2009). "We conclude that Sp1 attracts CD8+C28− T cells into the peritoneal cavity that modulate CD4+ T cell-dependent abscess formation." (PMID 19779562, 2009). "The intraperitoneal application of Sp1, as a positive control, induced abscesses with a median abscess size of 4 mm (one abscess/mouse), and the application of SCC alone and SCC plus mSp1 as negative controls, did not induce abscess formation." (PMID 19779562, 2009). "The median abscess size of Sp1-challenged mice is 2 mm (one abscess/mouse)." (PMID 19779562, 2009). "In the experimental model of abscess induction, CD8+CD28− Ts represent a small population with about 0.1% of cells migrating into the peritoneal cavity upon Sp1 challenge." (PMID 19779562, 2009). "Application of adjuvant alone and chemically modified Sp1 (mSp1) plus adjuvant, as negative controls, do not induce abscesses." (PMID 19779562, 2009). "In contrast to the adoptive transfer of Sp1-induced CD8+CD28+ T cells that together cause intraperitoneal abscesses with a median abscess size of 4 mm, transfer of Sp1-induced CD8+CD28− T lymphocytes significantly inhibited the abscess formation (no abscess detected)." (PMID 19779562, 2009).
acute leukemia (1 paper, 2018). A clonal (malignant) hematopoietic disorder with an acute onset, affecting the bone marrow and the peripheral blood. "Because miR-29b is a negative regulator of Sp1 gene in acute leukemia cells, the future work may need to identify whether miR-29b is involved in the niclosamide-mediated decrease in Sp1 in CML cells." (PMID 29358661, 2018).
adrenal tumor (1 paper, 2025). "However, one study reported that Sp1 and SF-1 interact through the N-terminal regions of NF-1 and the DBD of Sp1, inducing CYP11A in Y1 adrenal tumor cells and bovine luteal cells." (PMID 39858066, 2025).
alcoholic steatohepatitis (1 paper, 2021). "In agreement with our findings, TG2 nuclear accumulation and crosslinked Sp1 were observed in the fibrotic area of patients with alcoholic steatohepatitis." (PMID 34360011, 2021).
Alcoholism (1 paper, 2018). "Among them, AD-specific module AD_M1 is regulated by SP1, TEAD4, PCBP1 with targets in the pathway of regulation of actin cytoskeleton, cAMP signaling pathway, PI3K-Akt signaling pathway, metabolic pathways, Alcoholism, and PPAR signalling pathway." (PMID 30598117, 2018).
Becker muscular dystrophy (1 paper, 2012). Becker muscular dystrophy (BMD) is a neuromuscular disease characterized by progressive muscle wasting and weakness due to degeneration of skeletal, smooth and cardiac muscle. "In addition, we also evaluated the mRNA expression of Sp1 and Cyclin D1 expression in mdx mice and patients with mild Becker muscular dystrophy (BMD) and severe Duchenne muscle dystrophy (DMD)." (PMID 22911796, 2012).
body-cavity-based lymphoma (1 paper, 2016). "Kaposi’s sarcoma-associated herpesvirus (KSHV) latent protein, latency-associated nuclear antigen (LANA), was also found to bind directly to Sp1 in KSHV-infected body-cavity-based lymphoma (BCBL) cells and enhance the binding of Sp1 to its cognate binding sites in the hTERT proximal promoter." (PMID 27548225, 2016).
bone cancer (1 paper, 2024). A primary or metastatic malignant neoplasm affecting the bone or articular cartilage. "Increased H3K27ac levels upon tumor infiltration enhance Sp1-mediated expression of the GPR160 in dorsal root ganglia, which contributes to bone cancer pain." (PMID 39448865, 2024).
bronchioloalveolar carcinoma (1 paper, 2009). A well or moderately differentiated morphologic variant of lung adenocarcinoma characterized by tumor growth along the alveolar structures without stromal, vascular, or pleural invasion. "Moreover, genistein can block the stimulation of VEGF gene transcription by all trans-retinoic acid through Sp1 and Sp3 sites in a human bronchioloalveolar carcinoma cell." (PMID 19742137, 2009).
cervical (1 paper, 2023). "Collectively, these findings indicate that Sp1 could promote cervical tumorigenesis by improving cell proliferation, migration, and invasion and inhibiting apoptosis." (PMID 37147632, 2023).
cervical adenocarcinoma (1 paper, 2023). An adenocarcinoma arising from the cervical epithelium. "Immunohistochemical (IHC) staining showed that the Sp1-positive score was higher in cervical squamous carcinoma and cervical adenocarcinoma tissues than in paracarcinoma tissues." (PMID 37147632, 2023). "In this study, we found that Sp1 was overexpressed both in human cervical squamous carcinoma and cervical adenocarcinoma tissues." (PMID 37147632, 2023). "The protein levels of Sp1 in human cervical squamous carcinoma, cervical adenocarcinoma, and para-carcinoma tissues were investigated." (PMID 37147632, 2023).
Chagas disease (1 paper, 2016). A parasitic infection caused by Trypanosoma cruzi. "The MYC/SP1 transcription factors that regulate hypoxia and oxidative/inflammatory stress were predicted to be key targets in the context of control of Chagas disease severity." (PMID 26919708, 2016).
chronic atrophic gastritis (1 paper, 2013). Atrophic gastritis that is persistent and long-standing. "In normal and chronic atrophic gastritis cases, SP1 expression was low in 89.5% and 83.3% of the samples, respectively." (PMID 23437057, 2013). "In normal tissues and chronic atrophic gastritis, SP1 expression was low." (PMID 23437057, 2013).
chronic obstructive pulmonary disease (1 paper, 2021). A chronic and progressive lung disorder characterized by the loss of elasticity of the bronchial tree and the air sacs, destruction of the air sacs wall, thickening of the bronchial wall, and mucous accumulation in the bronchial tree. "Here, we are trying to explore whether the high expression of p16 mediated by p300/Sp1 can cause chronic obstructive pulmonary disease through promoting the senescence of endothelial progenitor cells (EPCs)." (PMID 34456628, 2021). "However, very limited researches were made upon the p300/Sp1-mediated high expression of p16 in endothelial progenitor cell senescence and the development of chronic obstructive pulmonary disease." (PMID 34456628, 2021).
Cirrhosis (1 paper, 2022). A chronic disorder of the liver in which liver tissue becomes scarred and is partially replaced by regenerative nodules and fibrotic tissue resulting in loss of liver function. "HIF-1α expression was correlated to poor prognosis of HCC patients with cirrhosis and high HIF-1α and Sp1 co-expression were also found to be associated with poorer prognosis of HCC patients." (PMID 36139684, 2022).
colorectal adenocarcinoma (1 paper, 2018). The most common type of colorectal carcinoma. "To determine whether ZEB2 expression correlates with Sp1 expression in human cancers, we analyzed TCGA-generated colorectal adenocarcinoma data (two cancer studies; TCGA, Nature 2012, and TCGA, Provisional)." (PMID 29416649, 2018).
diabetic neuropathy (1 paper, 2011). A chronic, pathological complication associated with diabetes mellitus, where nerve damages are incurred due to diabetic microvascular injury involving small blood vessels that supply these nerves, resulting in peripheral and/or autonomic nerve dysfunction. "Based on the present results, compounds that bind to a SP1-7-specific binding site, like Phe-Phe amide, might be attractive for the treatment of pain symptoms associated with diabetic neuropathy." (PMID 22040520, 2011).
dilated cardiomyopathy (1 paper, 2024). Cardiomyopathy which is characterized by dilation and contractile dysfunction of the left and right ventricles. "Furthermore, the involvement of SP1 in diseases like dilated cardiomyopathy and other arrhythmias should be validated through fundamental and clinical experiments." (PMID 39062521, 2024).
dissection (1 paper, 2023). The separation and isolation of tissues for surgical purposes, or for the analysis or study of their structures. "Downregulation of miR-124 and Sp1 levels was found in human aortic media from clinical specimens of aortic dissection." (PMID 36836777, 2023).
Fanconi anemia (1 paper, 2020). Fanconi anemia (FA) is a hereditary DNA repair disorder characterized by progressive pancytopenia with bone marrow failure, variable congenital malformations and predisposition to develop hematological or solid tumors.
female reproductive cancers (1 paper, 2021). "Adding to this, a second P2-promoter SNP, MDM2 SNP285C, lowers Sp1 binding and essentially counteracts the increased affinity of SP1 for the MDM2 SNP309G, located 24 base pairs downstream (as reported in female reproductive cancers)." (PMID 33664771, 2021).
fibrocarcinoma (1 paper, 2013). "Moreover, the CUR significantly reduced colony formation; results are in agreement with other studies demonstrating that downregulation of Sp-1 prevents the colony formation in a patient derived fibrocarcinoma cell line." (PMID 23970932, 2013).
gallstones (1 paper, 2025). Solid crystalline precipitates in the biliary tract, usually formed in the gallbladder, resulting in the condition of cholelithiasis. "While earlier studies have demonstrated that RBL1‐T369 phosphorylation releases E2F transcription factors, we found that phosphorylation at this site also releases Sp1, allowing it to drive MUC1 transcription during gallstone formation." (PMID 39932450, 2025).
germ cell tumours (1 paper, 2016). "PARP1 regulates FBN1 gene expression through Sp1 and these data suggest, that increased PARP expression in neoplastic cells in germ cell tumours can lead to increased FBN1 gene expression." (PMID 27487789, 2016).
hearing loss (1 paper, 2023). "In an animal acute LPS-induced hearing loss model, the histone deacetylase 2 Hdac2/transcription factor Sp1/miR-204-5p/apoptosis suppressor gene Bcl-2 regulatory axis mediated apoptosis in the cochlea." (PMID 37181652, 2023).
hemorrhagic cystitis (1 paper, 2020). Inflammation of the bladder resulting in bloody urine. "Moreover, a potential association, between a C/G mutation in the NCCR Sp1 site and increased BKPyV virulence in hemorrhagic cystitis (HC) patients, has been proposed." (PMID 32375383, 2020).
hepatitis B (1 paper, 2023). "In fact, SP1-mediated HBV replication can be targeted with drugs that can treat hepatitis B. Screening for alpha-glucosidase (AG) inhibitors against the HBV infection in hepatocytes identified one candidate inhibitor that lowered ccc DNA production through binding to SP1." (PMID 36902112, 2023).
heroin addicts (1 paper, 2026). "Another study in heroin addicts found, however, that the OPRM1 promoter was also hypermethylated, with increased density around the Sp1 transcription factor binding site, directly inhibiting the binding of the transcriptional machinery." (PMID 41596476, 2026).
Hyperammonemia (1 paper, 2019). An increased concentration of ammonia in the blood. "The relevance of the findings for understanding the role of Sp1 in the regulation of SN1 transporter and SN1-mediated Gln uptake in the brain during hyperammonemia in vivo remains to be documented using more native systems." (PMID 30634395, 2019).
Hyperoxaluria (1 paper, 2025). Increased excretion of oxalates in the urine. "Further studies are required to explore the novel role of calcium, MAPKs, and ROS in Sp1 function in terms of H2S production in hyperoxaluria." (PMID 41008994, 2025). "Here, we showed consistent results in another kidney disease model, indicating that hyperoxaluria and oxalate markedly suppressed Sp1 protein levels and activities." (PMID 41008994, 2025). "Due to the upstream function of transcription factor Sp1 on regulating H2S-producing enzyme expression, we investigated whether hyperoxaluria affects Sp1 activity." (PMID 41008994, 2025). "Although the present study did not directly investigate how hyperoxaluria and oxalate impair Sp1 expression and activity, previous studies have provided several upstream mechanisms that may contribute to altered Sp1 activity." (PMID 41008994, 2025).
insomnia (1 paper, 2024). A sleep disorder characterized by difficulty in falling asleep and/or remaining asleep. "A transcription factor (TF)–target analysis of the TRRUST database reveals that numerous targets are regulated by TFs such as NFKB1, RELA, SP1, JUN, and others, suggesting that these TFs may play an important role in insomnia." (PMID 38927034, 2024).
intrahepatic cholangiocarcinoma (1 paper, 2014). A carcinoma that arises from the intrahepatic bile duct epithelium in any site of the intrahepatic biliary tree. "Moreover, ERBB2 signaling pathway enriched by SP1 and ELK1 has been implicated in the molecular pathogenesis of intrahepatic cholangiocarcinoma by interacting with other relevant signaling pathways, including linking to bile acid, vascular endothelial growth factor signaling." (PMID 24897108, 2014).
ischemia reperfusion injury (1 paper, 2025). Adverse functional, metabolic, or structural changes in ischemic tissues resulting from the restoration of blood flow to the tissue (reperfusion), including swelling; hemorrhage; necrosis; and damage from free radicals. "Specificity protein 1 (SP1) mediates ferroptosis induced by ischemia-reperfusion injury after MI by enhancing the transcription of USP46 and inactivating AMPK signaling." (PMID 40384965, 2025).
ischemic cardiomyopathy (1 paper, 2022). Ischemic cardiomyopathy is a cardiomyopathy in which a weakness in the muscle of the heart due to inadequate oxygen delivery to the myocardium with coronary artery disease being the most common cause. "Scatter plot analysis showed a significant positive correlation between Ndufs1 and Sp1 mRNA levels in NF subjects and HF patients; similar results were obtained in patients with ischemic cardiomyopathy." (PMID 35817848, 2022).